ENSG00000202517
Synonyms: LOC124900557
Gene: Small nucleolar RNA gene on chromosome 3 (40,238,608 to 40,238,741, forward strand). Ensembl gene ENSG00000202517.
Gene Ontology:
Biological process: RNA processing
Cellular component: nucleolus
Homologues: Paralogues in human: SNORA64 (81% identical), SNORA10 (58% identical), SNORA10B (58% identical).